MMP2 (matrix metallopeptidase 2)
Diseases named in the same sentence as MMP2 in open-access papers (continued):
Sharing a sentence is not in itself a finding about the gene and the disease.
glioblastoma (continued). "In oesophageal squamous cell carcinoma (ESCC) and glioblastoma (GBM), SRGN can indirectly upregulate the expression of MMP2/MMP9 by activating the ERK pathway, TGF‐β signalling, or the CXCLs/CXCR2 axis, thereby enhancing tumour invasion and metastasis." (PMID 41410182, 2025). "Tenascin-C induced increased expression of the active form of MMP-2 in glioblastoma cells, which was supposed to contribute to continuous PDGF production suggesting a positive feedback loop of tenascin-C/TNIIIA2/PDGF leading to hyper-proliferation of glioblastoma cells." (PMID 35008401, 2022). "In addition, studies on glioblastoma have also reported that CCR7 activates TGF-β1-induced invasion, migration, and epithelial-mesenchymal transformation of human malignant gliomas by activating MMP2/9 and the nuclear factor KappaB signal transduction pathway." (PMID 35996545, 2022). "The correlation analysis observed that SCIN positively correlated with the expression of MMP2 (Spearman correlation coefficient r = 0.357, p < 0.001) and MMP9 (Spearman correlation coefficient r = 0.356, p < 0.001) in TCGA RNA seq datasets for glioblastoma and low-grade glioma (TCGA GBMLGG)." (PMID 36291348, 2022). "In glioblastoma cells, Trop2 promotes growth and dissemination by the activation of the JAK2/STAT3 signaling pathway and attenuates the expression of molecules downstream of this signaling pathway such as cyclin D1, survivin, matrix metalloproteinase 2 (MMP2), and vascular endothelial factor (VEGF)." (PMID 33187148, 2020). "Accordingly, MMP-2 downregulation does not exclusively occur in endothelial cells, but has also been shown to occur in lysates and culture media from cancer cells such as glioblastoma cells exposed to 25 μM cisplatin." (PMID 30344920, 2018). "Thus, COE may inhibit MMP-2 and MMP-9 activity and ECM hydrolysis, thereby attenuating the invasion and migration of glioblastoma cells." (PMID 27716341, 2016). "Therefore, the invasion of glioblastoma stimulated by Bcl-w is mediated by a cellular signaling pathway that involves the translocation of nuclear β-catenin via activation of PI3K/Akt and sequential upregulation of MMP-2 and FAK signaling components." (PMID 23826359, 2013). "Furthermore, in glioblastoma cell lines, it was demonstrated that Cyclosporin A affects migration and invasion by impairing PI3K/AKT pathway and the reduced cell motility correlates to diminished MMP2 gelatinolytic activity and to downregulated NF-kB activation." (PMID 34066419, 2021). "LGMN has been determined to be highly expressed in many solid tumors, including colorectal cancer, breast cancer and glioblastoma (GBM), and high expression of LGMN correlated with a more metastatic phenotype, which is partially mediated by the activation of cathepsins and pro-MMP2." (PMID 34966781, 2021). "Further analyses indicated an effect of enhancing the sensitivity of glioblastomas cells in radiotherapy by E. ulmoides flavonoid, which might refer to downregulating HIF-1α/MMP-2 pathway, as the data showed the expressions of HIF-1α and MMP-2 were further reduced after the combination treatment." (PMID 34362420, 2021). "Matrix-metalloproteinase could degrade extracellular matrix proteins to overcome the physical barrier for glioblastoma cells, and studies showed that MMP2 and MMP9 could be regulated by several pathways such as Wnt and PI3K/AKT to promote GBM invasiveness." (PMID 30420967, 2018).
glioblastoma (continued). "This study aimed to compare the levels of matrix metalloproteinases (MMP2 and MMP9), terminal complement complex (C5b-9), and VEGF-A in circulating sEVs in glioblastoma patients (GBMPs) with and without tumor recurrence." (PMID 39996852, 2025). "CTR-GNPs decreased the mRNA levels of MMP-2/-9 and PLD1 in human U87 glioblastoma cells treated with or without PMA." (PMID 32074974, 2020). "Importantly, treatment with CTR-GNPs significantly decreased the levels of metalloproteinase (MMP)-2/-9 and phospholipase D1 (PLD1) and protein but not PLD2, which is involved in the modulation of migration and the invasion of glioblastoma cells." (PMID 32074974, 2020). "In addition, the activity of matrixmetalloproteinases MMP2, 9, and 3 play a pivotal role in this scenario: if agrin is cleaved by MMP3 —such as in glioblastoma—no typical OAPs are found and if MMP2 and 9 cleave dystroglycan —such as in glioblastoma—no OAPs are formed as well." (PMID 27483250, 2016).
osteosarcoma (200 papers, 2009 to 2026). A usually aggressive malignant bone-forming mesenchymal neoplasm, predominantly affecting adolescents and young adults. "Upregulation of MMPs, including MMP‐2 and ‐9, is associated with aggressive pediatric sarcomas like osteosarcoma, leading to poor prognosis and pulmonary metastasis." (PMID 40079158, 2025). "Further investigation is necessary to fully understand the underlying mechanisms and the role of MMP‐2 in modulating osteosarcoma cell migration." (PMID 38064181, 2023). "They found that fibulin-3, through the induction by NF-κB signaling, mediated the crosstalk between AEG-1 and MMP-2 and was associated with poor prognosis of osteosarcoma due to invasion and metastases." (PMID 35473807, 2022). "While in osteosarcoma, a predominant MMP-2/MMP-9 activity is associated with poor response to chemotherapy." (PMID 35047406, 2021). "In summary, our data showed that naringin inhibits the malignant phenotype of osteosarcoma cells by inhibiting the expression of Zeb1 and Zeb1-associated proteins such as Cyclin D1 and MMP2." (PMID 30580326, 2018). "For example, the expression of various MMPs, such as MMP-1 and MMP-2 was associated with poor prognosis in osteosarcoma and soft tissue sarcoma." (PMID 29316907, 2018). "For osteosarcoma, several studies have shown that highly invasive osteosarcomas express higher levels of MMP-2 than weakly invasive tumors, and osteosarcoma cell invasion is associated with MMP-2 expression." (PMID 29761075, 2018). "Here, we demonstrated that the ability of halofuginone to inhibit the TGF-β/Smad3 cascade in osteosarcoma reduces the expression and activity of MMP-2, a protein highly implicated in the migration and invasion processes." (PMID 26015407, 2015). "The MMP-2 expression level in osteosarcomas was significantly associated with the T stage and metastasis." (PMID 25605016, 2015). "Here, we confirmed the association between EFEMP1, AEG-1 and MMP-2 in tissue specimens of osteosarcoma patients." (PMID 25987128, 2015). "Deguelin significantly inhibited migration and invasion of U-2 OS human osteosarcoma cells which was associated with a reduction of activities of matrix metalloproteinases-2 (MMP-2) and matrix metalloproteinases-9 (MMP-9)." (PMID 25322282, 2014). "Previous studies have suggested a link between the increased expression of several MMPs, such as MMP-2, and osteosarcoma invasiveness, leading us to investigate the association between B7-H3 and MMP-2." (PMID 23940627, 2013). "In addition, the collagenase encoded by MMP2 has been associated with osteosarcoma pulmonary metastasis." (PMID 37938582, 2023). "Notably, the antimigratory effect of the synthetic cannabinoid WIN 55,212-2 on osteosarcoma cells was associated with downregulation of MMP-2 and -9 and a 700-fold upregulation of miR-29b1, a key miRNA that downregulates MMP-2 and -9." (PMID 35277658, 2022). "In addition, higher expression of COLGALT2 was found to be associated with higher levels of vimentin and MMP2/9 in osteosarcoma cells." (PMID 32523950, 2020). "First, we evaluated the MMP-2 activity that plays an important role in the invasive process of osteosarcoma cells." (PMID 40038783, 2025). "The evaluation of the logFC of the mmp‐2 gene and its isoforms (mmp‐2‐1, 3A, and 3B) was conducted in cancer cell lines and biopsies of osteosarcoma tumors from the PRJNA698672 and PRJNA518013 projects of the ENA‐EMBL." (PMID 40079158, 2025). "Our study reveals on the complex interplay among NaVs, NHE, and MMP‐2, offering valuable insights into cancer progression and suggesting promising avenues for early therapeutic interventions in osteosarcoma." (PMID 40079158, 2025). "Bioinformatic analysis pinpointed MMP‐2 as a biomarker for osteosarcoma metastasis, with both FL‐ mmp‐2 and NTT‐mmp‐2 isoforms identified in biopsies." (PMID 40079158, 2025).
osteosarcoma (continued). "Recently, a study showed that NAA10 promotes the invasion and metastasis of osteosarcoma cells by N-terminally acetylating matrix metallopeptidase 2 (MMP-2), thereby preventing its degradation." (PMID 40558489, 2025). "In osteosarcoma, upregulation of MMP-2, MMP-9, and MMP-13 has been observed in the presence of RUNX2, which promotes metastasis and invasion." (PMID 40806771, 2025). "In summary, this study confirmed that NGF suppresses the synthesis of miR-92a-1-5p via the MEK/ERK signaling cascade, thereby promoting the MMP-2-dependent migration of osteosarcoma cells." (PMID 38816365, 2024). "In the current study, NGF promoted the phosphorylation of MEK and ERK, while pharmacological inhibitors and siRNA targeting MEK and ERK inhibited NGF-induced MMP-2 expression and the migration of osteosarcoma cells." (PMID 38816365, 2024). "NGF induced MMP-2 expression in both osteosarcoma cell lines as well as increases in MMP-2 mRNA and protein levels in a dose-dependent manner." (PMID 38816365, 2024). "Third, the effect of the MMP2 inhibitor marimastat on the invasion and migration of osteosarcoma cells in mice injected with LRP1–SNRNP25-overexpressing osteosarcoma cells was not evaluated." (PMID 38678020, 2024). "Our in vitro results showed that the fusion gene LRP1–SNRNP25 promotes the invasion and migration of osteosarcoma cells by increasing the pJNK/37-kDa laminin receptor precursor (37LRP)/MMP2 protein levels." (PMID 38678020, 2024). "In the current study, we explored the involvement of MEK/ERK signaling in moderating the NGF-induced promotion of MMP-2-mediated wound healing, as well as the migratory and invasion abilities of osteosarcoma cells." (PMID 38816365, 2024). "This research also provided evidence that NGF significantly downregulates the expression of miR-92a-1-5p, thereby promoting MMP-2 expression and osteosarcoma metastasis." (PMID 38816365, 2024). "Immunohistochemical (IHC) staining of the osteosarcoma tissue array using MMP-2 antibodies revealed a notable correlation between MMP-2 expression and the clinical stage of the disease." (PMID 38816365, 2024). "Our study found that ITGB1 regulates MMP2 expression, which modulates the malignant phenotype of osteosarcoma." (PMID 38664375, 2024). "Collectively, these findings indicate that the LRP1–SNRNP25 fusion gene promotes the invasion and migration of osteosarcoma cells through the pJNK/37LRP/MMP2 signaling pathway." (PMID 38678020, 2024). "Our research identified the targeting of MMP-2 depletion as a novel therapeutic approach to the treatment of osteosarcoma metastasis." (PMID 38816365, 2024). "The fact that MEK inhibitors also suppress NGF-induced ERK phosphorylation suggests that MEK-dependent ERK activation mediates the NGF-promoted synthesis of MMP-2 and osteosarcoma cell motility." (PMID 38816365, 2024). "Transfection of osteosarcoma cells with a miR-92a-1-5p mimic significantly reduced NGF-induced MMP-2 mRNA and protein expression, as well as the cell migration and invasion abilities." (PMID 38816365, 2024). "PLK1 knockdown significantly reduced matrix metalloproteinase‐2 (MMP2) mRNA and protein levels in osteosarcoma cells." (PMID 38780513, 2024). "Aripiprazole has been shown to inhibit metastatic behavior in human osteosarcoma cells by reducing MMP-2 and MMP-9 expression levels and activity." (PMID 38816365, 2024). "The synergistic effect of targeting the MMP2 gene in combination with Doxorubicin for treating osteosarcoma has been previously examined." (PMID 39358756, 2024). "We also observed high expression levels of NGF and MMP-2 proteins in late-stage tumor samples in an osteosarcoma tissue array." (PMID 38816365, 2024). "The results revealed that the expression levels of MMP-2, -9, -13, and -14 mRNA are significantly higher in osteosarcoma tissue than in normal bone tissues." (PMID 38816365, 2024).
osteosarcoma (continued). "Recent studies have demonstrated that CTGF stimulates the formation of new blood vessels, enhances the production of MMP-2/3, and promotes the movement of cells in osteosarcoma." (PMID 39154307, 2024). "This study is the first to demonstrate a potential miR-92a-1-5p/MMP-2 regulatory axis involved in metastasis of osteosarcoma." (PMID 38816365, 2024). "This analysis revealed that NGF promotes osteosarcoma cell metastasis by upregulating MMP-2 expression." (PMID 38816365, 2024). "Immunohistochemical staining revealed significantly lower levels of MMP-2 in primary tumors in the genistein group, indicating that genistein attenuated the metastatic potential of osteosarcoma." (PMID 39335164, 2024). "MEK and ERK inhibition significantly attenuated the effects of NGF in promoting MMP-2 mRNA expression and migratory and invasion activity in osteosarcoma cells." (PMID 38816365, 2024). "This study demonstrates that H3NT proteolysis occurs in a cell density dependent manner in U2OS osteosarcoma cells, by the primary protease MMP-2 and the secondary and novel protease CTSB." (PMID 37161413, 2023). "FOXM1 has been proved to function via promoting the expression of c-Jun N-terminal kinase (JNK1) and matrix metalloproteinase 2 (MMP-2) in osteosarcoma." (PMID 37069649, 2023). "Our study was conducted in cell line model of osteosarcoma, therefore, further preclinical and clinical studies are warranted to evaluate MMP‐2 inhibitors as potential adjuvants to chemotherapy in osteosarcoma." (PMID 38064181, 2023). "We show that enhanced osteosarcoma cell migration which is induced by sublethal concentrations of doxorubicin can be overcome by inactivating the MMP‐2 gene or overexpressing CHK/MATK." (PMID 38064181, 2023). "In osteosarcoma tissues, MMP-2/9 contributes to the invasion of endothelial cells by destroying extracellular collagen." (PMID 36765716, 2023). "To further examine the effect of MMP‐2 KO on the migratory ability of osteosarcoma cells, we conducted wound closure assays on both the WT and MMP‐2 KO cells for the duration of 48 h until complete wound closure was observed in the WT." (PMID 38064181, 2023). "In our previous studies, we reported that in an osteosarcoma cell line, nuclear MMP‐2 regulates ribosomal RNA transcription through histone clipping, thereby modulating gene expression and cell proliferation." (PMID 38064181, 2023). "To this end, we leveraged the recent finding that MMP-2 is the principal H3NT protease in the human U2OS osteosarcoma cell line with a native ChIP-Seq approach to map the genomic sites targeted for MMP-2 mediated H3NT proteolysis." (PMID 37161413, 2023). "Recent findings indicate that MMP‐2 is also present in various subcellular compartments, including the nuclei of various cells such as osteosarcoma U2OS cells." (PMID 38064181, 2023). "Studies have determined that aprepitant has the ability to inhibit the migrative ability of osteosarcoma tumor cells and reduce the levels of matrix metalloproteinases (MMP-2 and MMP-9), as well as NF-κB, a known stimulator of metastasis-related genes." (PMID 36983138, 2023). "In summary, this study investigates the role of MMP‐2 in cancer migration and metastasis in osteosarcoma." (PMID 38064181, 2023). "Leveraging recent findings that matrix metalloproteinase 2 (MMP-2) functions as the principal nuclear H3NT protease in the human U2OS osteosarcoma cell line, a ChIP-Seq approach was used to map MMP-2 localization genome wide." (PMID 37161413, 2023). "Silencing the tumor suppressor SERPINB1 and MMP-2 induction induces the invasion and metastasis ability of osteosarcoma cells." (PMID 38031146, 2023). "By targeting the MMP‐2 gene, we can potentially enhance the effectiveness of doxorubicin treatment and reduce chemoresistance in osteosarcoma." (PMID 38064181, 2023). "In osteosarcoma, piperine inhibited cell migration by reducing the expression of MMP2 and MMP9 and increasing the expression of TIMP1 and TIMP2." (PMID 36678600, 2023).